TERT (telomerase reverse transcriptase)
Diseases named in the same sentence as TERT in open-access papers (continued):
Sharing a sentence is not in itself a finding about the gene and the disease.
glioblastoma (continued). "Arora et al45 recently demonstrated that patients with glioblastoma multiforme and hepatocellular carcinoma with east Asian ancestry had lower frequency of TERT promoter mutations compared to patients with European ancestry." (PMID 37462445, 2024). "TERT-p mutations are frequently found in low-grade and glioblastoma tumors, but they are associated with a contrary prognosis." (PMID 38893240, 2024). "The diffuse astrocytoma, IDH-wild-type, WHO grade II, as well as the anaplastic astrocytoma IDH-wild-type WHO grade III, will both become glioblastoma IDH-wild-type CNS WHO grade 4 if they feature TERT promoter mutation, EGFR amplification, and/or +7/−10)." (PMID 39057054, 2024). "The composition of TERT mutations within the entire glioblastoma cohort (n = 101) included promoter mutations (n = 89; 88.12%), promoter mutations in the setting of TERT amplification (n = 9; 8.91%), and missense mutations (n = 3; 2.97%)." (PMID 38665799, 2024). "For example, glioblastoma patients with both TERT promoter mutations and EGFR amplification or wild-type IDH often have a worse prognosis compared to those with tumors with only one of these alterations." (PMID 39767571, 2024). "As seen for glioblastoma, TERT promoter mutations can be investigated by DNA sequencing, while CDKN2A/B status can be assessed by multiple tools including DNA NGS and FISH." (PMID 37658995, 2024). "As a crucial diagnostic and prognostic biomarker, telomerase reverse transcriptase (TERT) promoter mutation holds immense significance for personalized treatment of patients with glioblastoma (GBM)." (PMID 38798094, 2024). "TERT promoter mutation shows very high incidence in glioblastoma but its highest incidence was also detected in the G1/EGFR-amplified subgroup." (PMID 38254850, 2024). "The presence of a TERT promoter mutation is specifically associated with a more favorable prognosis in glioblastomas with IDH mutations." (PMID 38932383, 2024). "To date, recent studies revealed that GABPB1L and TRIM28 had the potential to be the therapeutic target for TERT promoter mutation‐positive patients with glioblastoma and bladder cancer, respectively." (PMID 38769666, 2024). "The detection sensitivity of epidermal growth factor receptor variant III (EGFRvIII) was improved by FUS-BBBO from 7% to 65%, and the telomerase reverse transcriptase (TERT) promotor mutation C228T from 14% to 46% in the mouse glioblastoma model." (PMID 38672658, 2024). "We were able to confirm the reclassification to glioblastoma in a large part of our cohort while also establishing the challenge our expert team faced in retrospectively testing TERT mutation in the preserved samples." (PMID 38672254, 2024). "HGAPs do not harbor EGFR amplification, polysomy 7/monosomy 10, and rarely harbor TERT promoter mutations (1.1%), which define molecular alterations for glioblastoma." (PMID 39335555, 2024). "Telomerase reverse transcriptase (TERT) promoter mutations are most commonly observed in malignant melanoma, uroepithelial bladder cancer, glioblastoma, mucinous liposarcoma, as well as in certain skin cancer and medulloblastoma subtypes." (PMID 38562417, 2024). "Patients with TERT promoter-mutated glioblastomas often experience shorter overall survival (OS) compared to those without the mutation." (PMID 39767571, 2024). "TERT promoter mutations (56.1%) are frequent in glioblastoma or, when concurrent with IDH mutation and 1p/19q co-deletion, which is not clinically available on FoundationOne CDx, point to oligodendroglioma." (PMID 37682776, 2024). "The advances in molecular biology have enabled an in-depth understanding of the pathogenetic mechanisms of glioblastoma, including mutations in the telomerase reverse transcriptase (TERT) promoter." (PMID 39131044, 2024).
glioblastoma (continued). "According to the latest WHO guideline, cases of IDH wild‐type diffuse astrocytomas with TERT promoter mutation should be categorized as GBM (Glioblastoma) or CNS WHO grade 4, even if their histological appearance suggests a lower grade." (PMID 37953502, 2024). "The 2021 WHO Classification of Primary CNS Tumors identifies TERT promoter mutations as crucial diagnostic markers for CNS tumors, particularly in oligodendroglioma, glioblastoma, and meningioma, with a high mutation frequency of 70% in glioblastomas." (PMID 39767571, 2024). "Point mutations in the TERT gene promoter, leading to increased telomerase activity, are found in 75% of oligodendrogliomas and primary glioblastomas." (PMID 38532312, 2024). "In both newly diagnosed glioblastoma and recurrent glioblastoma, the TERT gene promoter mutation is commonly conserved, leading to an aggressive, highly proliferative phenotype." (PMID 38928445, 2024). "In some tumors, like glioblastomas, alterations of the gene encoding TERT, such as TERT promoter (TERTp) mutations or methylation at the TERTp, can cause the overexpression of TERT and confer a proliferative advantage to neoplastic cells." (PMID 39518074, 2024). "Analysis of the ORIEN glioblastoma cohort identified 28 genes mutated significantly more frequently in tumor samples; some included genes with known roles in glioblastoma including TERT, PTEN, and EGFR." (PMID 38665799, 2024). "Frequent and diagnostically relevant molecular alterations in IDH-wildtype glioblastomas include TERT promoter mutations, EGFR gene amplification, and copy number gain in chromosome 7 combined with copy number loss in chromosome 10 (+7/−10 genotype)." (PMID 38201434, 2023). "On the other hand, high rates of TERT promoter mutations were identified in some tumour types including glioblastoma, bladder cancer, cutaneous melanoma, hepatocellular carcinoma and squamous cell carcinoma (SCC) of the skin and oral mucosa." (PMID 38033865, 2023). "TERT promoter mutations are a hallmark of glioblastoma, enabling TERT expression, telomerase activity and telomere maintenance." (PMID 36997627, 2023). "They sampled ipsilateral normal SVZ tissue at a distance from the tumor and observed that glioblastoma driver mutations, such as TERT promoter mutations, were detectable in 56.3% of IDH wild-type patients." (PMID 36980563, 2023). "For instance, mutations in the TERT promoter are particularly prevalent in melanoma, TERT expression is often increased by a factor of four, and > 80% of primary glioblastomas exhibit TERT promoter mutations." (PMID 38270117, 2023). "The presence of TERT promoter mutations has been associated with worse prognosis and resistance to therapy for patients with glioblastoma (GBM)." (PMID 38054695, 2023). "Two genes, MTND6P33 and RNU1-2, were specific to glioblastoma patients with TERT promoter mutations and MGMT methylation." (PMID 37568598, 2023). "Eight genes, AC016737.2, BNC2-AS1, AC007040.1, AC009248.3, SOCAR, LAGE3, TOMM20L, and FP671120.11, were specific to patients with IDH1-wt and TERT-promoter-mutated glioblastoma." (PMID 37568598, 2023). "Here, we perform a narrative review investigating the biological role of TERT alterations on glioblastoma and the principal obstacles associated with TERT inhibitions in this population." (PMID 38201248, 2023). "In contrast, 4 cases shared age (> 40), pathological features of glioblastoma, and were TERT-mutated." (PMID 36647073, 2023). "These two tumors had the combination of trisomy chromosome 7 and monosomy chromosome 10 along with genetic alterations typical of conventional IDH-wildtype glioblastoma (e.g., TERT promoter mutation, CDKN2A/B homozygous deletion, EGFR amplification)." (PMID 38079020, 2023).
glioblastoma (continued). "We replicated most of these associations in glioblastoma (Klughammer cohort) where 14 of 17 genes were also positively associated with TERT expression, including four genes related to DNA repair (XRCC2, MSH5, TRAIP, BRIP1)." (PMID 37418389, 2023). "Conversely, in glioblastomas the rate of serum high telomerase expression level was notably lower (36%) from the rate of tumor TERT promoter mutations (79.6%)." (PMID 38155481, 2023). "In particular, for glioblastomas, a significantly higher number of neutrophils was confirmed in cases with TERT mutation." (PMID 38275375, 2023). "A panel consisting of 20 of 569 genes detected glioblastoma TERT promoter mutations with 89% sensitivity and 100% specificity." (PMID 37568598, 2023). "The LASSO regression to predict TERT promoter mutation status (predicting TERT mutant glioblastoma compared to control samples) revealed 20 predictor genes that together yielded 89% sensitivity and 100% specificity when applied to the test dataset." (PMID 37568598, 2023). "Group 2 was made up of 4 cases (cases #1 to #4) that shared old age (> 40 years), pathological features of glioblastoma, presence of TERT promoter mutation, and chromosome + 7/−10." (PMID 36647073, 2023). "TERT promoter mutations are among the most frequently mutated genomic regions in many types of malignant tumors such as glioblastoma, hepatocellular carcinoma, thyroid carcinoma, and UC." (PMID 37598154, 2023). "TERT mutations are found in many glioblastomas, whereas mutations of the X-linked gene of α-thalassemia (ATRX), leading to inactivation of the ATRX protein and induction of ALT, are found in many IDH-mutated astrocytomas." (PMID 37626776, 2023). "Progression to anaplastic oligodendroglioma is associated with additional genetic changes, such as loss of chromosome 9p, resulting in deletion of the CDKN2A tumor suppressor gene and the same TERT promoter mutations detected in glioblastoma." (PMID 36768856, 2023). "Point mutations within the TERT promoter are the most recurrent somatic noncoding mutations identified across different cancer types, including glioblastoma, melanoma, hepatocellular carcinoma, and bladder cancer." (PMID 37918959, 2023). "TERT promoter mutation is found in ~ 85% of IDH-wildtype glioblastomas and > 95% of IDH-mutant and 1p/19q co-deleted oligodendrogliomas." (PMID 37919784, 2023). "We also noticed many co-occurring TERT mutations in EGFR fusion samples, however, this is likely due to the high representation of glioblastomas, which frequently have TERT mutations." (PMID 37168365, 2023). "There are several known mechanisms that upregulate TERT transcription, but the one which has been largely investigated in both meningiomas and glioblastomas is related to TERT promoter mutation." (PMID 38155481, 2023). "Overactivation of TERT due to TERT mutation in glioblastoma cells increased FAS levels and lipid accumulation, which in turn were reduced by a TERT inhibitor." (PMID 37626776, 2023). "Mutations in the TERT promoter region cause an upregulation of telomerase, which leads to telomere maintenance and oncogenesis seen in many tumor types, including glioblastoma." (PMID 38201434, 2023). "In HNSCC, TERT promoter mutations are moderately frequent (range 17–32%) compared to melanoma, glioblastoma, and bladder cancer, but more frequent in recurrent vs. non-recurrent squamous cell carcinoma of the oral cavity." (PMID 36909826, 2023). "TERT mutations have the highest prevalence in glioblastoma, liposarcoma, oligodendroglioma, urothelial carcinoma, melanoma, and hepatocellular carcinoma." (PMID 37892022, 2023).
glioblastoma (continued). "By WGS data, TERT hotspot mutations were found in 74% of primary glioblastoma cases in a previous study, and these mutations resulted in increased TERT RNA expression." (PMID 36333792, 2022). "To better evaluate the impact of TERT mutations on survival, we assessed which patient characteristics were associated with survival in TERTmut and TERTwt IDHwt glioblastoma patient cohorts." (PMID 36380219, 2022). "More importantly, GABPB1 knockout inhibits TERT expression and telomerase activity in TERT promoter-mutated glioblastoma cells, disrupting telomere length maintenance through which apoptosis is induced." (PMID 35326537, 2022). "In this study, we have used extensively EGFR amplification and 10q loss in addition to TERT, as 10q loss has been shown to be associated with glioblastomas for many years." (PMID 35558510, 2022). "Of interest, several studies found a prognostic interaction of TERT promoter mutation with MGMT promoter methylation in patients with IDHwt glioblastoma treated with radiochemotherapy." (PMID 34902093, 2022). "TERT promoter mutations can occur early in the tumor and are considered to be one of the major mutations in tumors such as melanoma, glioblastoma, and hepatocellular carcinoma." (PMID 35903534, 2022). "Ki-67 index and TERT or IDH mutation are positively associated with overall survival of glioblastoma patients and a lower Ki-67 index and IDH-wildtype are linked with poor prognosis." (PMID 36566187, 2022). "TEERA is an enzyme activated in this process creating an R-loop that escorts the telomere lengthening process alongside TERT triggering, which is highly implicated in glioblastomas." (PMID 35806478, 2022). "The TERT promoter mutations were found to be the most common point mutations in several types of cancer, including 60–100% of glioblastoma, 22–71% of melanoma, 29–100% of bladder cancer, and 29–65% of hepatocellular carcinoma cases." (PMID 35135543, 2022). "As is the case with EGFR amplification, diffuse gliomas formerly classified as IDH-wildtype grade 2–3 diffuse astrocytomas with TERT promoter mutations are now classified as glioblastomas, IDH-wildtype." (PMID 35693015, 2022). "In this study, prognosis in glioblastoma cases with TERT mutation was worse than in oligodendrogliomas with TERT mutation." (PMID 34558656, 2022). "TERT promoter mutations occur in about 70% of glioblastoma, IDH-wildtype and in >95% of oligodendrogliomas, IDH-mutant and 1p/19q-codeleted." (PMID 35693015, 2022). "Some previous studies identify TERT mutation status as an independent predictor of poor survival in IDHwt glioblastoma patients, while others find that it is confounded by other genes." (PMID 36380219, 2022). "In particular, both clonal and subclonal mutations of TERT are associated with poor prognosis of bladder cancer and glioblastoma (P-value = 0.003 and P-value = 0.011, respectively)." (PMID 35962343, 2022). "According to CN5S (2021), the diagnosis of IDH wild-type glioblastoma is based on the presence of EGFR amplification or TERT promoter mutation, or the combined gain of the whole chromosome 7 and the loss of whole chromosome 10 (+7/−10)." (PMID 35806478, 2022). "In 13 IDH-wildtype glioblastomas with chromosome 10 losses and TERT promoter mutations (10 tumors with “C228T”, 3 tumors with “C250T”) we compared the TERT promoter MAFs with the deleted allele frequencies on chromosome 10 as detected by ddPCR." (PMID 35361262, 2022). "For example, diffuse astrocytomas with lower histologic grade and IDH wild type with TERT promoter mutation are classified as glioblastoma in the 2021 fifth edition classification." (PMID 36081550, 2022). "While TERT mutations are one of the characteristic mutations in IDHwt glioblastomas, their prognostic significance remains controversial." (PMID 36380219, 2022).
glioblastoma (continued). "Here, the authors identify TERT promoter duplications across seven cancer types that are functionally equivalent to well-known hotspot TERT mutations and are clonal in a multifocal glioblastoma patient." (PMID 36114166, 2022). "Since the long variant of GABPB1 mRNA (GABPB1L) but not its shorter transcripts was observed to play a functional role in the activation of the mutated TERT promoter in glioblastoma, we further determined GABPB1L expression in the same tumors." (PMID 35326537, 2022). "This argues against standardized analysis for TERT promotor mutation status for the purpose of prognostic or therapeutic relevance in newly diagnosed IDH-wildtype glioblastoma that otherwise meets the histopathological and molecular diagnosis criteria." (PMID 36325373, 2022). "TERT promoter mutations result in an unlimited proliferative capacity of tumor cells and have been reported in up to 80% of glioblastoma." (PMID 35436952, 2022). "Patients with CDKN2A copy loss (HR 2.963, p = 0.0037) or TERT mutated (HR 2.815, p = 0.0008) glioblastomas exhibited significant associations between radiation dose and OS, while CDKN2A and TERT wild type patients did not." (PMID 36380219, 2022). "Approximately 70–90% of glioblastomas have mutations in the TERT promoter (C228T or C250T) located at −124 bp and −146 bp upstream of the TERT translation start site (5p15.33)." (PMID 35806478, 2022). "TERT promoter mutations have been previously identified in glioblastoma (84%), urothelial carcinoma (64.5%), oligodendroglioma (70.0%), medulloblastoma (33.3%) and hepatocellular carcinoma (31.4%)." (PMID 36313663, 2022). "In recent years, numerous molecular alterations, including IDH mutations and TERT-p, were identified and added to the primary and secondary glioblastomas’ core molecular landscape." (PMID 34884508, 2021). "Alternatively, we report the first case of glioblastoma with TERT amplification accompanied by multiple TERT and FGFR2 gene fusions instead of TERTp mutation." (PMID 34976798, 2021). "Another recently described signalling pathway in glioblastoma is the telomerase-related senescence escape pathways through mutation of the ATRX (alpha thalassemia/mental retardation syndrome X-linked) gene or TERT (telomerase reverse transcriptase) promoter." (PMID 34683160, 2021). "TERT promoter mutations and their expression have been reported as prognostic factors in several tumors, including glioblastoma and malignant melanoma." (PMID 34477310, 2021). "Recently, TERT rearrangements, which are mutually exclusive with TERT promoter mutations, have been identified in some aggressive cancers such as glioblastoma, neuroblastoma and melanoma as late driver mutations." (PMID 34062862, 2021). "TERT promoter mutation has been extensively evaluated in different tumors: thyroid, glioblastoma, urothelial, melanoma, among others." (PMID 32850388, 2020). "Glioblastomas also are reported to present a poor prognosis in patients harboring TERT mutations, which were commonly evaluated in combination with IDH and MGMT methylation." (PMID 32850388, 2020). "TERT promotor mutations that reactivate telomerase in glioblastoma have occasionally been identified in adult ependymoma, but not in children." (PMID 33115534, 2020). "In contrast with adult glioblastoma, mutations within the promoter region of the telomerase catalytic subunit, TERT, leading to its overexpression, occur at a lower rate in pediatric tumors (3–11% compared to 55–83% in adult tumors)." (PMID 32331249, 2020).